CD38 (CD38 molecule)
Diseases named in the same sentence as CD38 in open-access papers (continued):
Sharing a sentence is not in itself a finding about the gene and the disease.
multiple myeloma (continued). "The high level of CD38 expression by immune cells in patients with myeloma may be a possible reason for the difference in the efficacy of CD38 inhibitors in NSCLC." (PMID 38348050, 2024). "However, normal plasma and multiple myeloma (MM) cells exhibit increased CD38 levels, making CD38 a suitable target for developing therapeutic antibodies against MM." (PMID 38983860, 2024). "Daratumumab is an anti‐CD38 drug that induces cell death in myeloma cells." (PMID 39157594, 2024). "Interestingly, several hematological malignancies (chronic myeloid leukemia, acute myeloid leukemia, acute lymphoblastic leukemia, and multiple myeloma) express CD38 at a high level." (PMID 38422172, 2024). "This is explainable by the fact that CD38, the type II transmembrane glycoprotein to which the mAb binds, is expressed on plasma cells, plasmablasts, and immature transitional B cells, and are highly present on malignant myeloma cells." (PMID 38793769, 2024). "Additionally, patients with penta-refractory myeloma (myeloma refractory to lenalidomide, pomalidomide, bortezomib, carfilzomib and an anti-CD38 MoAb) have an even more grim prognosis with a median OS of about 6 months with subsequent therapies." (PMID 38660139, 2024). "CD38 is expressed not only on myeloma cells but also on NK cells." (PMID 38284882, 2024). "Daratumumab, a human IgG1 monoclonal antibody that specifically binds to a unique epitope present on the CD38 molecule, induces, at least, a partial response in up to 30% of refractory multiple myeloma, due to its action on CD38-positive plasma cells, with a good safety profile." (PMID 39534185, 2024). "Altogether, these data suggest that tinostamustine could be a potential candidate for improving the anti-myeloma efficacy of anti-CD38 mAbs, such as daratumumab or isatuximab, in the clinical setting." (PMID 38731936, 2024). "The observed phenomenon might be due to the samples being predominantly composed of myeloma cells, thereby attracting more antibodies, even though the antibodies for CD38 detection were carefully titrated before use." (PMID 39493694, 2024). "Lastly, it is currently unknown whether exercise mobilises NK-cells or monocytes in myeloma patients, nor whether the mobilisation of these daratumumab effector cells has the potential to enhance anti-CD38 mAb therapy against circulating myeloma cells." (PMID 39411424, 2024). "We considered whether any hits associated with these pathways may be “druggable,” with the goal of expanding our repertoire of small molecules that enhance surface CD38 in myeloma." (PMID 40453054, 2024). "Multiple myeloma (MM), a plasma cell malignancy, has seen dramatic improvements in survival over the last two decades with the advent of immunomodulatory agents, proteasome inhibitors, and anti-CD38 targeted monoclonal antibodies." (PMID 39095991, 2024). "We next tested whether T cell–engaging SAR442257 yields greater multiple myeloma cell cytotoxicity than the CD38 antibodies that are important components of current clinical care." (PMID 38421887, 2024). "CD38 is a surface protein that is expressed on plasma cells and multiple myeloma (MM) cells." (PMID 38448430, 2024). "SAR442257 shows promise for multiple myeloma and may be best suited for patients declared resistant to both CD38 mAbs and BCMA-targeted therapy." (PMID 38421887, 2024). "Here, we use Myeloma Drug Sensitivity Testing (My-DST) for ex vivo measurement of anti-multiple myeloma cytotoxicity for the trispecific CD38/CD28xCD3 TCE SAR442257 through activation of the patients’ own endogenous T cells to inform clinical development of the compound in multiple myeloma." (PMID 38421887, 2024). "Our studies here present a “multiomics” view of therapeutically targeting CD38 in multiple myeloma." (PMID 40453054, 2024). "CD38 is a well-established target in multiple myeloma, and effective CD38 retreatment strategies would be a timely development in the changing landscape of multiple myeloma treatment." (PMID 38421887, 2024).
multiple myeloma (continued). "In addition, there is potential for the effectiveness of HA in combination with other anti-myeloma drugs, including lenalidomide, anti-CD38 antibodies, and steroids." (PMID 39695174, 2024). "The authors suggested that the non-significant increase in CDC may be the result of a smaller relative increase in the expression of CD38 induced by ATRA treatment when compared to other myeloma cell lines such as, XG119." (PMID 39548231, 2024). "Despite this, CD38 expression on multiple myeloma cells remained bright." (PMID 38421887, 2024). "Are there other features of myeloma surface remodeling driven by CD38 downregulation?" (PMID 40453054, 2024). "For example, daratumumab, a mAb targeting CD38 is being tested in multiple myeloma (MM) in combination with FT576, a B cell maturation antigen (BCMA) specific CAR NK with high-affinity, non-cleavable CD16, and a knockout of CD38 (to prevent fratricide) (NCT05182073)." (PMID 38545115, 2024). "Consistently, daratumumab, a monoclonal antibody against CD38, reacted with CD38 expressed on monocytes and inhibited in vitro osteoclastogenesis and bone resorption of mononuclear cells harvested from the bone marrow of multiple myeloma patients." (PMID 39180173, 2024). "Malignant PCs in MM and AL amyloidosis share several key features which are of relevance to immunotherapeutic approaches, including the surface expression of CD38, B-cell maturation antigen (BCMA), and G-protein-coupled receptor, class C group 5 member D (GPRC5D)." (PMID 38672686, 2024). "BM MSCs move mitochondria to myeloma cells via TNTs, initiated by CD38 expression on myeloma cells." (PMID 36795453, 2023). "However, lenalidomide (LEN) refractoriness remains an important factor affecting the therapeutic efficacy of both PI and IMiD, even after another class of anti-myeloma therapeutics, such as anti-CD38 MoAbs, are available." (PMID 38004369, 2023). "Tecvayli: BCMAxCD3 bispecific for the treatment of adult patients with relapsed or refractory multiple myeloma who have received at least four prior lines of therapy, including a proteasome inhibitor, an immunomodulatory agent, and an anti-CD38 monoclonal antibody." (PMID 37304291, 2023). "Studies have shown the efficacy of treatments targeting CD38 molecules in multiple myeloma." (PMID 37649020, 2023). "1q21 gain also induces the JAK-STAT pathway, which reduces CD38 expression in myeloma cells." (PMID 37173885, 2023). "Low levels of CD38 expression on myeloma cells during daratumumab treatment are hypothesized to be due to trogocytosis of the CD38‐daratumumab complex by monocytes and granulocytes, whereby a cell extracts and ingests “bites” of material from another cell." (PMID 37840445, 2023). "Multiple myeloma(MM) cells express CD38 in high levels, whereas the expression levels of CD38 are lower in normal myeloid and lymphoid cells as well as some non-hematopoietic tissues, driving the development of anti-CD38 monoclonal antibodies (mAbs) in the treatment of MM." (PMID 38116009, 2023). "Despite the recent approval of novel immunotherapies, such as immunomodulatory drugs, proteasome inhibitors and anti-CD38 monoclonal antibodies, Multiple Myeloma (MM) remains incurable, and the acquisition of triple-refractoriness leads to really dismal outcomes in even earlier lines of therapy." (PMID 37296910, 2023). "These cells could successfully lyse the primary human multiple myeloma cells and deplete CD38+ myeloma cells in human bone marrow-derived samples." (PMID 36761751, 2023). "Targets expressed in normal bone marrow plasma cells can be divided in those in which expression in myeloma cells remains stable in later stages in longitudinal samples (i.e., CD38, CS1, BCMA, FCRH5, CD74, CD79B), and those for which expression is stage-dependently lost (e.g., CD19, CD22, BAFF-R)." (PMID 38035078, 2023). "Daratumumab is a CD38-directed monoclonal antibody indicated to treat multiple myeloma (MM)." (PMID 36910662, 2023).
multiple myeloma (continued). "Patients with RRMM who reported failing two lines of anti-myeloma treatment (immunomodulatory agent and a proteasome inhibitor [PI]) or ≥ 3 lines (including ≥1 PI, immunomodulatory agent, or anti-CD38 monoclonal antibody), were recruited across the US, UK, Italy, Germany, France, and Spain." (PMID 38076274, 2023). "Other target antigens: BCMA and CD38 are also found on myeloma cells." (PMID 36717905, 2023). "Lenalidomide upregulated the expression of CD38 on the surface of myeloma cells, and the combination of Daratumumab with lenalidomide/dexamethasone or other drugs such as bortezomib/dexamethasone are continuously carried out and they can significantly improve the clinical outcomes of patients." (PMID 37275861, 2023). "CD38, a transmembrane glycoprotein that expresses in myeloid and lymphoid cells with high levels in plasma B-cells, is a promising target for anti-CD38 therapy in Myeloma." (PMID 37735675, 2023). "The expression of the transmembrane glycoprotein CD38 is well documented in hematological cancers, including multiple myeloma (MM), certain types of lymphoma, and leukemia; the prevalence and expression level of CD38 is lower and more variable in non‐MM cancers." (PMID 36251503, 2023). "Furthermore, CD38hi Tregs from either myeloma patients or healthy donors have increased suppressive function, and CD38-blocking antibodies are able to reduce their function." (PMID 36669118, 2023). "The DREAMM-2 clinical trial evaluated the efficacy and safety of belantamab mafodotin in patients with relapsed or refractory multiple myeloma who had received at least three prior lines of therapy, including an IMiD, a PI, and an anti-CD38 monoclonal antibody." (PMID 37511588, 2023). "CD38 is highly expressed mainly in multiple myeloma and chronic B-cell leukemia." (PMID 36879313, 2023). "Notably, another in vitro study showed that vitamin D increases vulnerability to anti-CD38 antibodies by enhancing CD38 expression on myeloma cells." (PMID 37181039, 2023). "Anti-CD38 MoAb represents a new treatment option for LEN-refractory myeloma." (PMID 38004369, 2023). "This case highlights the need to add a panel of plasma cell markers when myeloma is suspected, and it is pertinent to read flow cytometry with caution to avoid missing atypical plasma cells which maybe CD38+/CD138-." (PMID 36810550, 2023). "Targeting CD38 is considered to have been a breakthrough in multiple myeloma immunotherapies." (PMID 38116009, 2023). "However, detecting multiple myeloma in daratumumab-pretreated patients remains difficult due to overlapping binding epitopes of the CD38-specific imaging antibody constructs and daratumumab." (PMID 36389758, 2022). "Multiple myeloma cells and other hematological malignancies overexpress CD38." (PMID 36405759, 2022). "However, CD38 expression on myeloma or NK cells can be balanced to favor myeloma killing by daratumumab." (PMID 35159200, 2022). "CD38 pharmacological inhibition has been largely studied in hematological malignancies, and different anti-CD38 monoclonal antibodies are currently in use for the treatment of multiple myeloma." (PMID 36497069, 2022). "Isatuximab is another anti-CD38 IgG kappa monoclonal antibody with a similar mechanism of action as daratumumab and is characterized by a strong anti-myeloma activity via direct tumor cell killing and a unique direct proapoptotic effect independent of Fc crosslinking." (PMID 35886976, 2022). "Of note, NK cells also express CD38 on their surface, albeit at a lower level than myeloma cells." (PMID 35159200, 2022). "CD38 is a glycoprotein that is highly and uniformly expressed in plasma cells in multiple myeloma." (PMID 35004078, 2022). "The cytotoxic effect of CD38-specific HLE-nano-BiKEs was tested on LP-1 luc myeloma cells." (PMID 35651607, 2022).
multiple myeloma (continued). "Liposomes modified with anti-CD38 or anti-CD138 monoclonal antibody could be a new approach for a targeted delivery system with both targeting myeloma cells and also delivery anticancer agents to cancer cells." (PMID 35209102, 2022). "Furthermore, scholars developed liposome‐based multispecific T‐cell engagers (nanoMuTEs), decorating with anti‐CD3 mAbs and multiple mAbs, including anti‐BCMA, anti‐CS1, and anti‐CD38 mAbs, against myeloma cells simultaneously." (PMID 35665368, 2022). "Our study suggests that it may be beneficial to evaluate the potential of more plasma cell-specific treatments, e.g., by use of CD38-specific antibodies some of which are currently in clinical trials for treatment of multiple myeloma." (PMID 35456020, 2022). "Finally, in multiple myeloma, the membrane protein CD38 was also reported to support TNT formation and mitochondrial transfer from bone marrow stromal cells, as shown in vitro and in vivo after implantation of CD38 KD cells in NSG mice." (PMID 35267518, 2022). "Similarly, treatment of myeloma cells with ATRA has been shown before to increase CD38 expression and improve efficacy of daratumumab in vitro and in vivo." (PMID 36052078, 2022). "CD38 is a major target for the therapy of multiple myeloma (MM)." (PMID 36389758, 2022). "Of note, scFv antibodies #9, #13 and #25 showed strong binding to CD38-negative U266 and INA-6 myeloma cell lines and therefore may be especially interesting for patients’ refractory to CD38 immunotherapy." (PMID 35784366, 2022). "Studies in patients with multiple myeloma have found that CD38+ T regulatory (Treg) cells are more suppressive than CD38− Treg cells, consisting of a novel subpopulation of Tregs (CD41CD251CD127dim), which demonstrated superior autologous T-cell inhibitory capacities." (PMID 36139103, 2022). "In NK cells, disruption of endogenous CD38 has enabled the design of cell products which, when combined with anti-CD38 monoclonal antibodies (mAbs), confer anti-myeloma specificity for antibody-dependent cellular cytotoxicity (ADCC) while shielding NK cells from CD38-mediated fratricide." (PMID 36483551, 2022). "Additionally, both daratumumab, a CD38 monoclonal antibody, and immune checkpoint inhibitors have shown to enhance T cell immunity against myeloma." (PMID 35454812, 2022). "Anti-CD38 monoclonal antibody outcome in multiple myeloma: upfront and relapsed indications." (PMID 36225211, 2022). "All three CD38 antibodies mediated significant ADCC of L-363 myeloma cells with comparable half-maximal (EC50 #5-CD38-IgG1 = 2.9 pM, EC50 daratumumab = 3.6 pM, EC50 isatuximab = 3.6 pM) and maximum killing (#5-CD38-IgG1 = 45.45 ± 1.31%, daratumumab = 41.97 ± 1.18%, isatuximab = 40.3 ± 0.95%)." (PMID 35784366, 2022). "Here too, the high solubility and easy reformatability could render nanobodies particularly suited as targeting modules for AAVs, e.g. to myeloma cells overexpressing CD38." (PMID 36405759, 2022). "In addition, Daratumumab reduces the types of inhibitory cells in the TME of multiple myeloma, i.e., it consumes immuno-suppressive cells such as CD38+ MDSCs, Tregs, and Bregs, and enhances anti-tumor activity." (PMID 35251964, 2022). "Daratumumab also targets CD38+ immune, non-myeloma cell populations." (PMID 36176763, 2022). "Therefore, we used calibrated flow cytometry on both cell lines and primary myeloma bone marrow aspirate samples from relapsed/refractory myeloma patients to assess CD38 and CD48 density." (PMID 36311892, 2022). "In addition, we identified an antibody (#5) binding to CD38, a well-established antigen on myeloma cells and targeted by the clinically approved IgG1 antibodies daratumumab and isatuximab." (PMID 35784366, 2022). "Multiple myeloma cells with high CD38 expression reduce the number and activity of NK cells." (PMID 36268017, 2022).
multiple myeloma (continued). "CD38+CD101+ T cells, which characterize a permanently dysfunctional population of T cells, previously linked to post-stem cell transplant relapse in multiple myeloma, were present in 22.02 ± 7.6% of late relapsed multiple myeloma CAR T cells compared with 6.39 ± 0.9% in HD products (NS)." (PMID 36874402, 2022). "First proof-of-concept studies performed to investigate the therapeutic potential of our newly identified antibodies revealed that #5-CD38-IgG1 had comparable affinity and potent anti-myeloma activity to the clinically approved CD38 antibodies daratumumab and isatuximab." (PMID 35784366, 2022). "CD38-specific nanobodies can be used either for the treatment of multiple myeloma by generation of nanobody-based heavy-chain antibodies (hcAbs), nanobody-based CARs, and nanobody-based BiKEs, or for in vivo imaging of multiple myeloma." (PMID 36389758, 2022). "Multiple myeloma and immunoglobulin light-chain amyloidosis may be effectively treated with anti-CD38 immunotherapy." (PMID 36077708, 2022). "Additionally, a recent study revealed that our nanobody JK36 detects myeloma cells from daratumumab-treated patients with greater sensitivity than a commercially available CD38-specific multi-epitope reagent." (PMID 36389758, 2022). "Hence, CD38-directed antibody therapy—besides targeting CD38-positive myeloma cells—can also restore an immunologically functional BMME exerting appropriate anti-MM T-cell responses." (PMID 35886976, 2022). "Apart from CD38 upregulation, Panobinostat exposure has led to several changes in transcriptional profile of myeloma cells, which may aid in overcoming drug resistance in MM, making it a promising candidate for drug combination treatments." (PMID 36139103, 2022). "Multiple myeloma is a plasma cell malignancy with a heterogeneous genomic profile that remains incurable despite the use of therapies such as alkylating agents, proteasome inhibitors, immunomodulatory drugs, and anti-CD38–targeted mAbs." (PMID 36874402, 2022). "The CD38 can drive mitochondrial trafficking in multiple myeloma, as well as after stroke." (PMID 36290721, 2022). "The role of CD38 in TIICs is consistent with elevated CD38 in a number of hematological cancers and the clinical effectiveness of anti-CD38 monoclonal antibodies (e.g., daratumumab) in treating multiple myeloma." (PMID 35677882, 2022). "Moreover, CD38 acts as a cell surface marker in hematologic malignancies such as multiple myeloma, the disease in the therapy of which cytotoxic anti-CD38 antibodies are used." (PMID 36077708, 2022). "Isatuximab is a CD38-directed cytolytic monoclonal antibody and is indicated in combination with dexamethasone and pomalidomide in the management of patients with multiple myeloma who have been previously treated with at least two prior agents, including a proteasome inhibitor and lenalidomide." (PMID 35371888, 2022). "Interestingly, novel studies in improving the efficacy of isatuximab led to the discovery of SAR442085, a novel anti-CD38 antibody with enhanced ADCC antitumor activity against multiple myeloma." (PMID 36077708, 2022). "In addition to many other advantages, the rationale for anti-CD38 combinations is the ability of some anti-myeloma therapies to increase the density of CD38 molecules on the MM cells." (PMID 35407416, 2022). "CD38 is highly expressed in hematological malignancies including multiple myeloma." (PMID 34539634, 2021). "Careful analysis of the outcome of the first clinical trials of single agent Daratumumab for treatment of relapsed/refractory myeloma revealed that patients with a high expression of CD38 by myeloma cells had a better chance of obtaining a response of PR or better." (PMID 33801271, 2021). "Indeed, CD38 monoclonal antibodies have shown high efficacies in multiple myeloma at different lines of therapy, which is exerted through both antibody-mediated cytotoxicity, as well as modulation of immune surveillance in the niche." (PMID 34764342, 2021).